ENSG00000201710
Synonyms: LOC124903420
Gene: Small nucleolar RNA gene on chromosome 14 (100,979,992 to 100,980,066, forward strand). Ensembl gene ENSG00000201710.
Gene Ontology:
Biological process: RNA processing
Cellular component: nucleolus
Homologues: Paralogues in human: SNORD114-17 (72% identical), SNORD114-12 (71% identical), SNORD114-3 (69% identical), SNORD114-23 (68% identical), SNORD114-11 (67% identical), SNORD114-13 (67% identical), SNORD114-18 (67% identical), SNORD114-21 (67% identical), SNORD114-14 (65% identical), SNORD114-15 (65% identical), SNORD114-19 (65% identical), SNORD114-26 (65% identical), and 27 more.